BCKDK (branched chain keto acid dehydrogenase kinase)
Diseases named in the same sentence as BCKDK in open-access papers (continued):
Sharing a sentence is not in itself a finding about the gene and the disease.
glioblastoma (2 papers, 2024 to 2025). The most malignant astrocytic tumor (WHO grade IV). "As in other cancers, BCKDK is linked to glioblastoma progression, with its knockout resulting in reduced tumor cell proliferation." (PMID 40507232, 2025). "However, elevated BCKDK levels suppress BCKA oxidation, which appears to contradict the findings of increased isotope-labeled BCKA incorporation in glioblastoma." (PMID 40507232, 2025). "Similarly, knocking down BCKDK results in a marked decrease in several intermediates of the TCA cycle and glycolysis, further supporting the role of BCAA metabolism in maintaining central carbon metabolism in glioblastoma." (PMID 40507232, 2025).
Hyperglycemia (2 papers, 2022 to 2025). An increased concentration of glucose in the blood. "As revealed by protein quantification, BCKDHA and BCKDHB were downregulated in diabetic retinas and hyperglycemia-induced Müller cells, whereas BCKDK levels increased." (PMID 39150511, 2025).
myocarditis (2 papers, 2017 to 2022). Myocarditis is a condition that is characterized by inflammation of the heart muscle (myocardium). "We demonstrate that BCKDk protein contains at least nine immunodominant epitopes, three of which, BCKDk 71–90, BCKDk 111–130 and BCKDk 141–160, were found to induce varying degrees of myocarditis in immunized mice." (PMID 28597552, 2017). "Three peptides—BCKDk 111–130, BCKDk 71–90 and BCKDk 141–160—were found to induce myocarditis in a descending order (7/10, 5/10, and 2/10), and the number of inflammatory foci in the respective groups were 5.29 ± 2.67, 2.20 ± 0.97, and 7.50 ± 6.50." (PMID 28597552, 2017). "We were able to identify three peptides that are capable of inducing myocarditis—BCKDk 71–90, BCKDk 111–130 and BCKDk 141–160—and BCKDk 111–130 being the efficient." (PMID 28597552, 2017). "As expected, the three peptides, BCKDk 71–90, BCKDk 111–130, and BCKDk 141–160 that induced myocarditis were also strong activators of T cells." (PMID 28597552, 2017). "In support of this proposition, antibodies for other mitochondrial proteins, such as ANT, BCKDk, pyruvate dehydrogenase, and mitochondrial M7, have been reported in DCM patients and/or CVB3 myocarditis." (PMID 36101433, 2022). "To test their ability to induce myocarditis individually, we selected a total of nine peptides, three from each of groups II (BCKDk 61–80, BCKDk 71–90 and BCKDk 91–110), III (BCKDk 111–130, BCKDk 121–140, and BCKDk 141–160) and VIII (BCKDk 331–350, BCKDk 341–360, and BCKDk 351–370)." (PMID 28597552, 2017).
nonalcoholic fatty liver disease (2 papers, 2022 to 2025). "Here, we aimed to determine whether circulating levels of the immediate substrates of BCKDH, the branched-chain α-keto acids (BCKAs), and hepatic BCKDK expression are associated with the presence and severity of nonalcoholic fatty liver disease (NAFLD)." (PMID 35797133, 2022).
type 2 diabetes (2 papers, 2024 to 2025). "A recent clinical trial demonstrated that the BCKDK inhibitor sodium phenylbutyrate can lower plasma BCAA levels in patients with type 2 diabetes." (PMID 40465706, 2025). "Therefore, liver-specific inhibition of BCKDK-mediated gluconeogenesis will provide a new strategy for the treatment of type 2 diabetes." (PMID 39389936, 2024).
autoimmune disease (1 paper, 2017). A disorder resulting from loss of function or tissue destruction of an organ or multiple organs, arising from humoral or cellular immune responses of the individual to their own tissue constituents. "BCKDk 111‐130‐induced inflammatory lesion contained both T cells and macrophages, suggesting that the disease pathogenesis involves the mediation of classic delayed hypersensitivity reaction as expected in T cell‐mediated autoimmune diseases." (PMID 28597552, 2017).
autoimmune hepatitis (1 paper, 2017). Hepatitis caused by autoantibodies. "Taken together, the data suggest that BCKDk 111–130 has a potential to induce autoimmune hepatitis in the immunized animals." (PMID 28597552, 2017). "Nonetheless, the finding that the number of liver foci were increased only in animals immunized with BCKDk 111–130 but not the other eight peptides and also an irrelevant antigen (RNase 43–56) suggests that BCKDk 111–130 also can be an autoantigen in the mediation of autoimmune hepatitis." (PMID 28597552, 2017).
autoimmune myocarditis (1 paper, 2017). Autoimmune myocarditis is an autoimmune disease that affects the heart. "In summary, we have shown that mitochondrial proteins like BCKDk can become immune targets in the mediation of autoimmune myocarditis and/or hepatitis by generating autoreactive T cells." (PMID 28597552, 2017).
colorectal adenocarcinoma (1 paper, 2020). The most common type of colorectal carcinoma. "Hence, we investigated whether phosphorylation of BCKDK at Y246 could be detected in metastatic HCT116, SW620, and LoVo colorectal adenocarcinoma cell lines." (PMID 32238881, 2020).
dermatomyositis (1 paper, 2024). Dermatomyositis (DM) is a type of idiopathic inflammatory myopathy characterized by evocative skin lesions and symmetrical proximal muscle weakness. "Data collected on juvenile dermatomyositis (JDM) and adult dermatomyositis showed a decrease in BCKDK expression." (PMID 39062842, 2024).
diabetic cardiomyopathy (1 paper, 2021). Diabetic cardiomyopathy is a disorder of the heart muscle in people with diabetes. "The real-time PCR results showed that BCAT2 and PP2Cm mRNA levels were lower and that BCKDK mRNA levels were higher in diabetic cardiomyopathy mice than in control mice." (PMID 34084135, 2021). "In addition, BCKDHA phosphorylation and BCKDK protein expression were increased, whereas BCAT2 and PP2Cm protein expression was decreased in diabetic cardiomyopathy mice." (PMID 34084135, 2021).
glioma (1 paper, 2023). A benign or malignant brain and spinal cord tumor that arises from glial cells (astrocytes, oligodendrocytes, ependymal cells). "Furthermore, the results of RT-qPCR suggested higher expression of BCKDK and UAP1L1 in TMZ resistant glioma tissues than in TMZ sensitive glioma tissues." (PMID 38054015, 2023).
Hepatitis (1 paper, 2017). Inflammation of the liver. "One of these, BCKDk 111–130, could also induce hepatitis without affecting lungs, kidneys, skeletal muscles, and brain." (PMID 28597552, 2017).
Huntington disease (1 paper, 2022). Huntington disease (HD) is a rare neurodegenerative disorder of the central nervous system characterized by unwanted choreatic movements, behavioral and psychiatric disturbances and dementia. "By measuring the blood of Huntington’s disease gene carriers and healthy controls in metabolites and gene expression changes, 6 statistically significant mRNA transcripts were found, and BCKDK was 1.34-fold higher in gene transcription level than healthy controls." (PMID 35923208, 2022).
invasive carcinoma (1 paper, 2022). A carcinoma that is not confined to the epithelium, and has spread to the surrounding stroma. "Among the genes involved in the initial 2 shared steps, the mRNA expression of BCAT2 and BCKDK was significantly higher, whereas the expression of PPM1K was lower, in the invasive carcinoma than that in normal breast tissue." (PMID 35785192, 2022).
juvenile dermatomyositis (1 paper, 2024). Juvenile dermatomyositis (JDM) is the early-onset form of dermatomyositis (DM), a systemic, autoimmune inflammatory muscle disorder, characterized by proximal muscle weakness, evocative skin lesion, and systemic manifestations. "Similarly, the GEO ID 56390258 data set was used to analyze BCKDK gene expression in skeletal muscle biopsies from patients with juvenile dermatomyositis." (PMID 39062842, 2024).
liver cancer (1 paper, 2020). An epithelial or non-epithelial malignant neoplasm that arises from the liver. "Therefore, the APN-mediated regulation of BCKDK activity in liver cancer may be related to its abnormal enzyme activity affecting BCAA catabolism homeostasis, and we plan to investigate this hypothesis in the future." (PMID 32457292, 2020).
liver diseases (1 paper, 2017). "The disease induced by BCKDk peptides could serve as a useful model to study the autoimmune events of inflammatory heart and liver diseases." (PMID 28597552, 2017).
lung carcinoma (1 paper, 2025). "Integrated genomics and metabolomics in lung cancer revealed BCKDK as an upstream regulator of MYC-dependent HK2 transcription, supporting dual BCKDK/HK2 inhibition to counter trametinib resistance." (PMID 40693266, 2025).
metastatic colorectal cancer (1 paper, 2020). "However, the profile of BCKDK in metastatic colorectal cancer (mCRC) remains unknown." (PMID 32238881, 2020).
morbid obesity (1 paper, 2020). An excess of body weight, normally defined as an individual with a body mass index greater than 35 or a body weight greater than one hundred percent of ideal body weight. "Concomitantly, the inhibitory kinase, BCKDK, was augmented in the obese patients (compared to non-obese) whereas, activating phosphatase PPM1K (protein phosphatase Mg2+/Mn2+ phosphatase) levels were reduced in morbid obesity (compared to both non-obese and pre-obese patients)." (PMID 32903728, 2020).
muscular disease (1 paper, 2024). Myopathy is a peripheral nervous system disease consisting of any abnormal condition or disease of the muscular tissues; commonly designates a disorder involving skeletal muscle. "Our study reveals a consistent association between decreased BCKDK expression and pathologic conditions impacting skeletal muscle, with particular relevance to muscular disease and aging models." (PMID 39062842, 2024). "We used the Gene Expression Omnibus Database to understand the role of BCKDK in skeletal muscle pathogenesis, including aging, muscular disease, and interrupted muscle metabolism." (PMID 39062842, 2024).
pancreatic cancer (1 paper, 2023). "The overexpression of BCKDK causes an excessive accumulation of BCAA, which has previously been reported to be associated with early events in pancreatic cancer development." (PMID 37460470, 2023).
renal failure (1 paper, 2025). "The locus shared between creatinine and cystatin C overlapped BCKDK (lead variant: rs117766531 on chromosome 16), a gene involved in acidosis and glucocorticoids metabolism, and catabolic signals associated with renal failure." (PMID 39927731, 2025).
rhabdomyosarcoma (1 paper, 2024). A rare aggressive malignant mesenchymal neoplasm arising from skeletal muscle. "The BCKDK gene expression was examined in human skeletal muscle biopsies from rhabdomyosarcoma patients compared to healthy controls, revealing a significant (p-value < 0.0001) decrease in gene expression." (PMID 39062842, 2024).
sarcoma (1 paper, 2024). A usually aggressive malignant neoplasm of the soft tissue or bone. "Decreased inhibition by BCKDK would allow dysregulated cells, such as sarcomas, to proliferate quicker than the native cells." (PMID 39062842, 2024).
Sepsis (1 paper, 2025). Sepsis is defined as life-threatening organ dysfunction caused by a dysregulated host response to infection. "Potentially also an increase in amino acid oxidation plays a role in the sustained acetyl-CoA concentration, as the gene expression of the oxidation-inhibiting enzyme BCKDK was suppressed in acute and prolonged sepsis." (PMID 39821755, 2025).
steatosis (1 paper, 2022). Increased lipid within the cytoplasm of cells. "Results from both cohorts were consistent with the strong associations observed for KIV BCKA/BCAA ratio with steatosis and NASH, showing significant positive associations between hepatic BCKDK gene expression and steatosis grade, ballooning, and NASH." (PMID 35797133, 2022). "Gene expression analysis in liver samples from 2 independent bariatric surgery cohorts showed that hepatic BCKDK mRNA expression correlates with steatosis, ballooning, and levels of the lipogenic transcription factor SREBP1." (PMID 35797133, 2022).
cancer (22 papers, 2020 to 2026). A tumor composed of atypical neoplastic, often pleomorphic cells that invade other tissues. "It should be noted that BCKDK has been associated with cancer risks and theoretically negatively regulates BCAA metabolism." (PMID 40507232, 2025). "Cancer cachexia is accelerated in muscle-specific BCKDK deficiency in mice after Lewis lung cancer cell transplantation." (PMID 39795113, 2024). "BCKDK is associated with various diseases, including proliferation, migration, and invasion in multiple types of human cancers." (PMID 37460470, 2023). "BCKDK has also been associated with cancer prognosis and malignancy." (PMID 39795113, 2024). "Recently, the overexpression of BCKDK has been linked to tumor progression in various cancers." (PMID 37460470, 2023). "BCKDK inhibitors may become future drug candidates for treating metabolic diseases and cancers caused by elevated branched-chain amino acid concentrations." (PMID 37460470, 2023). "Preclinical studies in HCC have also shown that turning BCKDH “back on” (via BCKDK inhibition or PPM1K activation) can suppress cancer aggressiveness." (PMID 41502503, 2025). "In the context of cancer biology, BCKDK has recently emerged as a metabolic node that intersects with oncogenic pathways." (PMID 40725241, 2025). "The nuclear presence of BCKDK is crucial for HRR and tumorigenesis, challenging traditional understanding and expanding therapeutic strategies targeting BCKDK in cancer." (PMID 40298908, 2025). "Another approach is to tie the BCKDK inhibitor to a tumor-targeting moiety (like an antibody or a ligand that the tumor uptakes), thereby concentrating it in cancer cells." (PMID 41502503, 2025). "BCKDK is crucial in the progression of various diseases through its metabolic functions, including diabetes, heart failure, and cancer." (PMID 40298908, 2025). "Apart from BCAA metabolism, BCKDK also regulates other cancer-relevant pathways through the direct phosphorylation of MEK and ATP citrate lyase." (PMID 36526674, 2023). "As discussed in the introduction, BCAA metabolism and BCKDK itself are deregulated in cancer and emerging as a potential new target in cancer." (PMID 36526674, 2023). "Two studies have recently identified different phosphorylation sites on BCKDK that mediates cancer proliferation, signaling and metastasis." (PMID 34526485, 2021). "Although the role of BCKDH complex and BCAT isoforms (cytosolic BCAT1 or mitochondrial BCAT2) have been widely explored in different cancers, the role of BCKDK remains mostly elusive." (PMID 34526485, 2021). "Loss of BCKDK led to reduced expression of BCAT1 and HIBCH, candidate genes augmented in several cancers." (PMID 34526485, 2021). "To gain comprehensive insight into the BCKDK signaling network, especially signaling involved in cancer cell metastasis, we combined BCKDK knockdown with phosphoproteomics analysis." (PMID 32238881, 2020). "In cancer models, BCKDK inhibition has produced some encouraging results." (PMID 41502503, 2025). "Similarly, BCKDK can enhance CAR-T-cell therapy efficacy, suggesting that more comprehensive studies on BCKDK inhibition regarding cancer and cancer immunity are necessary." (PMID 40507232, 2025). "Indeed, studies have found that high BCKDK and low PPM1K (indicating suppressed BCAA catabolism) are associated with more aggressive cancers and poorer patient survival." (PMID 41502503, 2025). "Notably, abnormal expression of BCKDK, phosphorylated RNF8 (p‐RNF8), and RAD51 are associated with cancer progression and patient outcomes." (PMID 40298908, 2025). "BCKDK is an attractive target to augment the sensitivity of cancer cells to paclitaxel." (PMID 36526674, 2023). "However, addition of BCAA decreased the synergy observed between both CMVA and DCBC in breast cancer cells, consistent with the BCKDKi working synergistically with paclitaxel through inhibition of BCKDK." (PMID 36526674, 2023).
cancer (continued). "However, as yet, the potential mechanisms of action of BCKDK in cancer progression and metastasis are unclear." (PMID 37460470, 2023). "Based on the available studies, the enzymes involved in the catabolism of BCAAs, such as BCAT1, BCAT2, and BCKDK, could be potential therapeutic targets for cancer treatment." (PMID 37637065, 2023). "Supporting this hypothesis, the BCKDK inhibitor BT2 recapitulates many of the effects of our AA mixture on cancer cells." (PMID 35367410, 2022). "Therefore, we investigated the role of BCKDK in human cancer and found that elevated BCKDK promoted CRC tumorigenesis by upregulating the MEK-ERK signaling pathway." (PMID 32238881, 2020). "Or does BCAT1 affects the activity of BCKDK in cancer development?" (PMID 32238881, 2020). "However, there is little research linking BCKDK and cancer, and the relationship between BCKDK and HCC is unclear." (PMID 32457292, 2020). "However, in the context of cancer therapy, one might use a BCKDK inhibitor in short bursts (e.g., a few days at a time) or in a localized manner." (PMID 41502503, 2025). "However, it remains unclear whether BCKDK promotes cancer growth primarily by suppressing BCKDH activity or through the stimulation of other kinase activity, such as ERK." (PMID 39795113, 2024). "However, the relevance of BCKDK to human cancer remains poorly understood." (PMID 32238881, 2020). "However, the mechanism by which abnormal BCKDK activity is produced in the course of cancer remains unclear." (PMID 32457292, 2020). "A framework is presented to categorize the differential reliance of various cancers on key catabolic enzymes-BCAT1, BCAT2 and BCKDK-underscoring their therapeutic vulnerability." (PMID 41769003, 2026). "Collectively, this study identified a novel downstream substrate of BCKDK and underscored the critical role of BCKDK/AKT signaling in RCC progression, providing a potential strategy for targeted cancer therapy." (PMID 40789057, 2025). "Earlier, we discussed how BCAT and BCKDK expression in various cancers influences BCAA metabolism, promoting cancer growth by reprogramming metabolic pathways." (PMID 40507232, 2025). "OE of Branched-Chain α-Ketoacid Dehydrogenase Kinase (BCKDK), a key enzyme in BCAA metabolism, significantly improved cancer cell lysis, while BCKDK KO resulted in inferior lysis potential." (PMID 41346587, 2025). "Cancer cells commonly upregulate BCAA metabolism through increased BCAT and BCKDK activity—driven by enhanced transcription, mRNA stability, and protein stability—to fuel their anabolic needs." (PMID 40507232, 2025). "BT2 and valsartan have been shown to inhibit BCKDK in vitro, and BT2 also increases the sensitivity of anti-cancer drugs in preclinical breast and ovarian cancer models." (PMID 40507232, 2025). "BCKDK, the key enzyme of BCAA metabolism, is reportedly highly expressed in colorectal, liver, lung, breast, and ovarian cancers." (PMID 39025830, 2024). "BCAT1 and BCKDK regulate the BCAA metabolism and cancer progression and have been identified as a marker for cancer prognosis." (PMID 37460470, 2023). "The branched-chain α-keto acid dehydrogenase kinase (BCKDK) plays an important role in many serious human diseases, including cancers." (PMID 35498541, 2022). "Since the EMT process appears to be critical to the metastasis of almost all carcinoma types, including CRC, we investigated the effects of BCKDK on the expression of EMT markers (E-cadherin, Vimentin, and N-cadherin)." (PMID 32238881, 2020). "Our study not only identified novel downstream phosphorylation substrates of BCKDK but also elucidated the critical role of the BCKDK/AKT axis in RCC progression, providing a potential therapeutic target for clinical intervention in cancer." (PMID 40789057, 2025). "BCKDK, a kinase that inhibits BCKDH activity, has received attention in cancer research." (PMID 40507232, 2025).